NLRP3 (NLR family pyrin domain containing 3)
Diseases named in the same sentence as NLRP3 in open-access papers (continued):
Sharing a sentence is not in itself a finding about the gene and the disease.
cardiovascular diseases (continued). "Expression of Nlrp3 inflammasome components in atherosclerotic plaques of patients correlates with cardiovascular disease severity, and NLRP3 expression in blood monocytes predicts adverse cardiac events." (PMID 35548412, 2022). "The NLRP3 inflammasome and downstream cytokines are emerging as important potential targets for cardiovascular disease." (PMID 32648087, 2021). "The repressive effect of BRB on NLRP3 inflammasomes in activated macrophages signifies its potential anti-atherogenic role in cardiovascular disease." (PMID 34684819, 2021). "Here, we examine the scientific evidence supporting a role for NLRP3 and the effects of inhibitors in cardiovascular diseases." (PMID 33673188, 2021). "Previous evidence implies an important role for the NLRP3 inflammasome in the pathogenesis of several cardiovascular diseases, such as atherosclerosis, atrial fibrillation and myocardial infarction." (PMID 33436548, 2021). "Studies suggested that NLRP3 inflammasomes and related pyrogenic signaling molecules played an essential role in the progression of cardiovascular diseases." (PMID 34901035, 2021). "NOD-like receptor pyrin domain containing 3 (Nlrp3) inflammasome is one of the identified proinflammatory signaling pathways involved in cardiovascular disorders and comorbidities, for example, metabolic syndrome and obesity." (PMID 34123416, 2021). "In order to address these concerns, multiple experimental studies are investigating the efficacy of utilizing pharmacological strategies to mitigate NLRP3-modulated inflammatory signals that promote further myocardial injury in cardiovascular diseases." (PMID 34207886, 2021). "The balance of opinion is predominantly in favor of the detrimental effect that the NLRP3 inflammasome contributes to the pathological process of cardiovascular disease and acknowledges that the NLRP3 inflammasome is a promising therapeutic target." (PMID 34567409, 2021). "Pharmacological strategies that specifically target the NLRP3 inflammasome has been investigated in several cardiovascular diseases." (PMID 34382743, 2021). "Recent preclinical studies support the potential therapeutic applicability of many existing drugs in blocking NLRP3 components as targets for treating cardiovascular disorders." (PMID 33923537, 2021). "To date, NLRP3 has been extensively studied in the heart, where its effects and actions have been broadly documented in numerous cardiovascular diseases." (PMID 34831246, 2021). "Expanding translational research with selective NLRP3 inhibitors is necessary to fully evaluate the potential of NLRP3 inflammasome inhibition in cardiovascular disease." (PMID 32648087, 2021). "Recent studies reported the role of the NLRP3 (nucleotide-binding domain, leucine-rich containing family, pyrin domain-containing-3) inflammasome in cardiovascular diseases and cardiac aging." (PMID 34439517, 2021). "Several studies have demonstrated the central role of NLRP3 inflammasome in cardiovascular diseases." (PMID 34382743, 2021). "In view of its importance and value in cardiovascular diseases, we systematically reviewed the recent research advances in NLRP3 inflammasome, particularly its specialized role in the cardiovascular diseases." (PMID 32377298, 2020). "We reviewed literature detailing pathological changes and molecular mechanisms associated with radiation-induced damage to the cardiovascular structure, with a specific focus on NLRP3 inflammasome-related cardiovascular diseases." (PMID 32226786, 2020). "Inflammation is an important process involved in several cardiovascular diseases (CVDs), and nod‐like receptor family pyrin domain containing 3 (NLRP3) inflammasome is a vital player in innate immunity and inflammation." (PMID 32508013, 2020). "IL-1β and IL-18, two key cytokines regulated by NLRP3 inflammasome activation, participate in endothelial inflammation and cardiovascular disease in humans." (PMID 32439949, 2020).
cardiovascular diseases (continued). "NLRP3 inflammasome activation has been shown to be involved in the pathogenesis of cardiovascular disease and vascular endothelial dysfunction." (PMID 32439949, 2020). "Recently, the role of the NLR family pyrin domain containing 3 protein (NLRP3) inflammasome has been studied in cardiovascular diseases." (PMID 31625260, 2020). "Researches on the role of NLRP3 inflammasome in the cardiovascular diseases are on the focus stage and have made a lot of great progress." (PMID 32377298, 2020). "We also provided insights into new treatment strategies for targeting NLRP3 inflammasome, as well as the upstream and downstream components of NLRP3 in alleviating cardiovascular diseases." (PMID 32377298, 2020). "In conclusion, the targeting the NLRP inflammasome in cardiovascular disease treatment holds promise, and the optimization of therapeutic approaches requires further clarification regarding the precise role of NLRP3 in cardiovascular disease." (PMID 32545788, 2020). "Our study showed that AE protected the expression of interendothelial junction proteins and restricted the release of HMGB1 by inhibiting the activation of NLRP3 inflammasome regulated by NLRP3 ubiquitination, and ultimately prevented cardiovascular disease." (PMID 32573820, 2020). "In this review, we summarized the role of NLRP3 in inflammatory response and discussed the relationship between NLRP3 and cardiovascular diseases." (PMID 32377298, 2020). "The NLRP3 inflammasome has been described as a key player in the development of cardiovascular disease." (PMID 31354519, 2019). "Previous studies have indicated that neurohumoral factors induce cardiovascular diseases through the NLRP3 inflammasome-related pathway." (PMID 30654511, 2019). "A growing number of studies have examined the relationship between the NLRP3 inflammasome and cardiovascular diseases (CVDs)." (PMID 31354731, 2019). "Increasing evidence suggests that the NLRP3 (nucleotide oligomerization domain-like receptor family, pyrin domain containing 3) inflammasome participates in cardiovascular diseases." (PMID 30906225, 2019). "In this review, we present the link between the NLRP subfamily and cardiovascular disease, with a focus on NLRP3, the most widely investigated member." (PMID 29850631, 2018). "MSC further reduced the gene expression of all NLRP3 inflammasome components and products, which relevance has been shown in different cardiovascular disorders besides myocarditis." (PMID 29434214, 2018). "Prospective randomized clinical trials including suitable clinical patient populations are needed to prove and validate the therapeutic potential of NLRP3 inflammasome inhibition for the management of cardiovascular diseases." (PMID 30150941, 2018). "In this context, activation of NLRP3 inflammasome mediating IL-1β and IL-18 secretion has emerged as an important component of inflammatory processes in cardiovascular diseases." (PMID 29245937, 2017). "Collectively, EXD may ameliorate myocardial damage in OVX rats through modulation of the gut microbiota and suppression of the TMAO-mediated NLRP3 inflammasome pathway, demonstrating its potential therapeutic implications for cardiovascular disorders." (PMID 41674055, 2026). "IL-6, as a risk biomarker for cardiovascular disease, may have a potential role in atherothrombotic complications, and NOD-like receptor protein 3 (NLRP3) inflammasome is an essential mediator of inflammatory response." (PMID 40827240, 2025). "Overview of completed clinical trials targeting the NLRP3 inflammasome in cardiovascular diseases." (PMID 40079000, 2025). "Its metabolic product TMAO is associated with cardiovascular diseases, and the latest research shows that TMAO may affect the function of pancreatic β-cells through the NLRP3 inflammasome." (PMID 40282416, 2025).
cardiovascular diseases (continued). "However, while evidence supports the role of DL-all-rac-α-tocopherol in inhibiting Lamtor1-HDAC6 interactions and reducing NLRP3 activation under inflammatory conditions, its effects on cardiovascular disease remain inconclusive." (PMID 40426881, 2025). "NLRP3 has undergone more study than other inflammasomes in cardiovascular disease." (PMID 40332346, 2025). "Recent findings shown that the NLRP3 inflammasome may play a role in radiation-induced cardiovascular diseases, drawing attention to it as a potential therapeutic target." (PMID 41272654, 2025). "In this regard, several clinical trials are currently evaluating immunomodulatory strategies in cardiovascular disease, including IL-6 blockade with ziltivekimab, selective NLRP3 inhibitors such as dapansutrile, and established anti-inflammatory agents such as colchicine and canakinumab." (PMID 40943136, 2025). "Moreover, we discuss the therapeutic potential of targeting NLRP3 to prevent radiation-induced cardiovascular diseases." (PMID 41272654, 2025). "A comprehensive analysis of the NLRP3 inflammasome and its role in radiation-induced cardiovascular diseases could provide valuable insights and establish the basis for innovative therapeutic approaches." (PMID 41272654, 2025). "Inflammation driven by proinflammatory polarized macrophages can promote cardiovascular disease via excessive activation of the NF-κB and NLRP3 inflammasome pathways, triggering the release of proinflammatory cytokines (IL-1β, IL-6, IL-18) and the generation of oxidative stress molecules." (PMID 40940785, 2025). "Consequently, intervening in the pathological progression in cardiovascular disorders by modulating NLRP3 inflammasome pathway emerges as a crucial protective measure." (PMID 38650918, 2024). "ROS has been identified as an important trigger for NLRP3 inflammasome activation in cardiovascular disease, which was further confirmed by immunofluorescent staining that showed CoQ10 treatment significantly suppressed the intracellular ROS production in macrophages both in vivo and ex vivo." (PMID 38281937, 2024). "Suppression of NLRP3 inflammasome components may provide prospective therapeutic targets for cardiovascular disease." (PMID 38224186, 2024). "Our data are in keeping with previous studies of CHIP in cardiovascular disease, and further studies into the therapeutic potential of NLRP3 inhibition for individuals with TET2 CHIP may be warranted." (PMID 38357791, 2024). "Furthermore, it explores potential therapeutic targets for VNS in modulating NLRP3 inflammasome, offering valuable insights for subsequent interventions in cardiovascular diseases through ANS-mediated NLRP3 inflammasome pathways." (PMID 38650918, 2024). "Consequently, within cardiovascular disease progression, NLRP3 inflammasome activation induced by excessive sympathetic activation is intricately linked to the progression of cardiovascular diseases." (PMID 38650918, 2024). "Since inflammation plays an important role as a key driver of AAAs, the regulation of NLRP3 inflammasome activation could be a promising therapeutic target for AAA-related cardiovascular diseases." (PMID 37958985, 2023). "Therefore, blocking the assembly and activation of NLRP3 inflammasome seems to be a new target for the treatment of cardiovascular diseases." (PMID 37600022, 2023). "The NLRP3 inflammasome is an intracellular multiprotein complex that promotes the maturation of inflammatory cytokines, such as IL-1β and IL-18, that are rapidly induced in cardiovascular diseases upon infection, trauma, or stress." (PMID 37373230, 2023). "In consequence, the NLRP3 inflammasome could mediate inflammation development as cardiovascular diseases progress." (PMID 37373230, 2023). "Consequently, inhibiting the activation of the NLRP3 inflammasome is crucial for the treatment of cardiovascular disease." (PMID 37370025, 2023). "This section mainly focuses on the NLRP3 inflammasome in cardiovascular disease." (PMID 37370025, 2023).
cardiovascular diseases (continued). "In addition, a large body of evidence from both clinical and experimental studies has shown that increased expression of NLRP3 inflammasome components; for instance, ASC, caspase-1 and NLRP3, is a relevant indicator of cardiovascular disease severity." (PMID 37958985, 2023). "Activation of the NLRP3 inflammasome has been shown to contribute to the development of a number of cardiovascular diseases (CVDs), representing a key pathogenetic mechanism in the formation and progression of atherosclerosis, and in the myocardial response to ischemic and nonischemic injury." (PMID 36618426, 2022). "From a clinical point of view, NLRP3 inflammasome activation has been suggested as a relevant indicator of cardiovascular disease severity and quantification of its components and end products in circulating cells and plasma/serum arise as novel potential biomarkers." (PMID 35204152, 2022). "The effects of MAMs-mediated ROS on the NLRP3 inflammasome in cardiovascular disease." (PMID 36588561, 2022). "The NLRP3-inflammasome and the interleukin 6 (IL-6)-pathways are central in cardiovascular disease." (PMID 36140297, 2022). "Are Btk involved in other cardiovascular diseases via NLRP3?" (PMID 35296647, 2022). "NLRP3 inflammasome pathways are closely related to most cardiovascular diseases." (PMID 35379787, 2022). "Both the NLRP3 inflammasome and its downstream cytokines, IL-1ß and IL-18, could therefore be promising targets in cardiovascular disease." (PMID 32648087, 2021). "The NLRP3 inflammasome has been reported as a therapeutic target in cardiovascular diseases." (PMID 34381021, 2021). "Taken together, these data indicate that inhibition of the Nlrp3 inflammasome may be a therapeutic strategy in Ang II-induced cardiovascular disease." (PMID 33628380, 2021). "In conclusion, animal models have demonstrated very robust evidence of a protective effect of NLRP3 inflammasome inhibition and the results of early clinical trials that aimed to limit the effects of the NLRP3 inflammasome in cardiovascular diseases are promising." (PMID 33673188, 2021). "In addition to chemotherapeutic drugs, natural products, and herbal drugs influence the NLRP3 pathway and can be potentially applied for cardiovascular disorders." (PMID 33923537, 2021). "In addition, NLRP3 inflammasomes mediated pyroptosis was observed in various cardiovascular diseases." (PMID 34901035, 2021). "Furthermore, TMAO promotes the release of inflammatory factors by activating the NLRP3 inflammasome, thereby promoting vascular calcification, myocardial fibrosis, and vascular inflammation aggravating cardiovascular disease." (PMID 34220546, 2021). "Thus, investigations into NLRP3 inflammasome will shed light on the pathogenesis of cardiovascular diseases and provide critical clues for seeking new targets for clinical cardiovascular diseases drug development." (PMID 32377298, 2020). "Activation of NLRP3 inflammasome is critical for the development of many cardiovascular disorders." (PMID 32508013, 2020). "Furthermore, treatments targeting the NLRP3 inflammasome are effective for the improvement of cardiovascular disease." (PMID 32581721, 2020). "The NLRP3 inflammasome may represent a molecular link between over nutrition, metabolic stress, inflammation and development of metabolic and cardiovascular diseases." (PMID 31379826, 2019). "NLRP3 inflammasome systematically exists in human organism, and its activation has been identified as initiation of numerous diseases, such as immune diseases, cardiovascular diseases, gut homeostasis, and even malignant cancers." (PMID 31428046, 2019). "The inhibition of NLRP3 activation may hold promise in the treatment of metabolic and cardiovascular diseases." (PMID 29245937, 2017).
cardiovascular diseases (continued). "In summary, our studies add novel data regarding protective mechanisms of dietary PUFA supplementation in cardiovascular disease, including activation of macrophage autophagy, improvement of mitochondrial function, and attenuation of the NLRP3 inflammasome activation." (PMID 28729463, 2017). "However, NLRP3 inhibitors have yet to be utilized in cardiovascular diseases." (PMID 39985261, 2025). "Therefore, regulating NLRP3 inflammasomes may be a potential target for prevention and treatment of cardiovascular diseases." (PMID 38172692, 2024). "Therefore, anti-inflammatory treatment targeting the NLRP3 inflammasome may become one of the most effective therapeutic approaches for cardiovascular disease." (PMID 39022620, 2024). "The traditional Chinese herbal naftoquinone compound Shikonin, extracted from the roots of Lithospermum erythrorhizon, displays numerous anti-inflammatory mechanisms by targeting NF-κB suppression and NLRP3 mediated IL-1β production; however, the effects on cardiovascular disease are still unknown." (PMID 37175869, 2023). "Thus, the targeted inhibitors to block the IL-1 isoforms and possibly oral NLRP3 inflammasome inhibitors may potentially target a wide spectrum of cardiovascular diseases." (PMID 35052846, 2022). "Accordingly, the inhibition or antagonism of NLRP3 could prevent cardiovascular diseases." (PMID 35035656, 2022). "FMT successfully inhibited the cardiac NLRP3 inflammasome and ultimately attenuated increased AF susceptibility and cardiac fibrosis, suggesting that FMT-targeted inhibition of the NLRP3 inflammasome is a new innovative therapeutic option for metabolic diseases and cardiovascular diseases." (PMID 36111168, 2022). "As a cytoplasmic receptor, NLRP3 responds to a series of molecules related to cellular ROS level and excessive production of pro-inflammatory cytokines, and mediates caspase-1-dependent programmed cell death, called pyroptosis, that plays an important role in cardiovascular disease." (PMID 35715805, 2022). "Hence, we hypothesized that the protective effect of AE on cardiovascular disease may be related to NLRP3 inflammasome." (PMID 32573820, 2020). "Here, we hypothesized that AE could improve endothelial junction dysfunction through inhibiting the activation of NOD‐like receptor family pyrin domain containing‐3 (NLRP3) inflammasome regulated by NLRP3 ubiquitination, and ultimately prevent cardiovascular disease." (PMID 32573820, 2020). "Thus, NLRP3 inflammasome may play a critical role in the cardiovascular diseases physiopathology and act as a proinflammatory mediator; it has become the focus of researchers in recent years." (PMID 32377298, 2020). "Clinical trials have confirmed that IL-1β and its receptor antagonist could be used to treat a variety of cardiovascular diseases, and the widely used drug glyburide played a crucial role in the treatment of cardiovascular diseases through the inhibition of the NLRP3 inflammasome." (PMID 32377298, 2020). "Effective regulation of NLRP3 may help prevent or even treat cardiovascular diseases." (PMID 32377298, 2020). "Nonetheless, we showed that Nlrp3 is involved in the regulation of arterial stiffening and cardiac remodeling, suggesting that Nlrp3 may be a therapeutic target for the prevention and treatment of cardiovascular disease." (PMID 27583382, 2016). "Chronic inflammation is an important contributor to the development of cardiovascular disorders, and inflammasomes, especially the NOD-like receptor protein 3 (NLRP3), are emerging as crucial mediators in this context." (PMID 40564905, 2025). "Therefore, NLRP3 inflammasome may become a promising target for cardiovascular diseases." (PMID 40827240, 2025). "This article reviews the nexus between NLRP3 inflammasome and cardiovascular disorders, elucidating the modulatory functions of the sympathetic and vagus nerves within the ANS with regard to NLRP3 inflammasome." (PMID 38650918, 2024).